MLKL (mixed lineage kinase domain like pseudokinase)
Diseases named in the same sentence as MLKL in open-access papers (continued):
Sharing a sentence is not in itself a finding about the gene and the disease.
non-alcoholic fatty liver disease (3 papers, 2021 to 2025). "MLKL deficiency has shown diverse effects in at least four separate studies of non-alcoholic fatty liver disease (NAFLD)." (PMID 34071602, 2021). "Although clinical applications of MLKL inhibitors remain limited, elevated systemic levels of RIPK1 and MLKL have been reported in patients with inflammatory conditions such as non-alcoholic fatty liver disease, highlighting their pathophysiological relevance." (PMID 41012357, 2025).
non-small cell lung carcinoma (3 papers, 2022 to 2025). A group of at least three distinct histological types of lung cancer, including non-small cell squamous cell carcinoma, adenocarcinoma, and large cell carcinoma. "In non-small cell lung cancer (NSCLC), reduced expression of RIPK3 and MLKL is significantly associated with poor patient prognosis, suggesting that pathway inactivation may promote tumor immune evasion." (PMID 41267084, 2025).
renal cell carcinoma (3 papers, 2017 to 2022). "Recent evidence revealed that cystine deprivation triggers RIP1/RIP3/MLKL-mediated necrosis in VHL-deficient renal cell carcinomas." (PMID 29383104, 2017). "To examine whether RIPK/MLKL-dependent necroptosis is involved in thrombus formation, we performed immunostaining of an autopsy sample of a patient with inferior vena cava thrombus due to renal cell carcinoma." (PMID 30062055, 2018). "In addition, emodin promotes the occurrence of necrotic apoptosis in renal cell carcinoma (RCC) cell lines, thereby restricting tumor development by inducing the production of ROS that promote increases in the levels of RIP1 and MLKL phosphorylation." (PMID 36497458, 2022).
rheumatoid arthritis (3 papers, 2017 to 2022). A chronic, systemic autoimmune disorder characterized by inflammation in the synovial membranes and articular surfaces. "Real-time transcription-polymerase chain reaction (RT-PCR) analysis was used to determine the expression of MLKL mRNA in PBMCs from 59 patients with SLE, 25 patients with rheumatoid arthritis (RA), and 30 age- and sex-matched healthy controls (HC)." (PMID 33054864, 2020).
tuberculosis (3 papers, 2017 to 2025). A chronic, recurrent infection caused by the bacterium Mycobacterium tuberculosis. "That may be what allows MLKL to exacerbate tuberculosis in mice that are prone to formation of necrotic lesions." (PMID 40950000, 2025).
ZIKV infection (3 papers, 2024 to 2025). "Additionally, we found that ZIKV infection does not significantly reduce the levels of phosphorylated MLKL (p-MLKL) induced by z-VAD-fmk combined with TNF plus SM164 (TSZ), indicating that ZIKV infection does not inhibit necroptosis." (PMID 39976465, 2025).
anemia (2 papers, 2021 to 2024). A reduction in the number of red blood cells, the amount of hemoglobin, and/or the volume of packed red blood cells. "We found that anemia and thymus atrophy were significantly exacerbated in Apcmin/+Mlkl-/- mice compared to Apcmin/+littermate controls, suggesting that loss of MLKL increased intestinal tumor development." (PMID 33767595, 2021).
autoimmune disease (2 papers, 2017 to 2024). A disorder resulting from loss of function or tissue destruction of an organ or multiple organs, arising from humoral or cellular immune responses of the individual to their own tissue constituents. "MLKL also plays an essential role in autoimmune disease by inducing embryonic lethality." (PMID 28860618, 2017).
autoimmune lymphoproliferative syndrome (2 papers, 2022 to 2023). Autoimmune lymphoproliferative syndrome (ALPS) is a rare, inherited disorder characterized by non-malignant lymphoproliferation, multilineage cytopenias, and a lifelong increased risk of Hodgkin's and non-Hodgkin's lymphoma. "A full decade before MLKL's role in cell death was discovered, inherited deficiency of Caspase 8 was reported to mediate autoimmune lymphoproliferative syndrome (ALPS)." (PMID 35166320, 2022).
B cell lymphoma (2 papers, 2018 to 2022). "SuDHL10 B-cell lymphoma cells have low or undetected levels of RIPK3 and MLKL." (PMID 29527209, 2018).
brain injury (2 papers, 2017 to 2024). Acute and chronic (see also brain INJURIES, CHRONIC) injuries to the brain, including the cerebral hemispheres, CEREBELLUM, and brain STEM. "Furthermore, activation of the RIP3/MLKL/TRPM7 pathway also worsens inflammation in brain tissue of rats suffering from traumatic brain injury." (PMID 39329120, 2024). "Promoting the degradation of MLKL may represent a novel avenue for reducing necrotic cell death after ischemic brain injury." (PMID 28978125, 2017).
cerebral infarction (2 papers, 2023 to 2025). An ischemic condition of the brain, producing a persistent focal neurological deficit in the area of distribution of the cerebral arteries. "Recent studies have shown increased expression of RIP1, RIP3, MLKL, as well as the interaction of RIP1 and RIP3 in rat models of cerebral infarction, indicating the involvement of necroptosis in the process of cerebral ischemia." (PMID 37904209, 2023). "Therefore, we hypothesized that the expression of MLKL in the ipsilateral thalamus is significantly up-regulated after cerebral infarction, and that MLKL interacts with Cx43 and regulates opening of Cx43 hemichannels, leading to intracellular calcium overload and neuronal necroptosis." (PMID 37904209, 2023).
chronic myelogenous leukemia (2 papers, 2020 to 2025). "However, we found unexpectedly that MLKL gene knockout enhanced CRC cell death caused by a protein synthesis inhibitor homoharringtonine used for chronic myeloid leukemia treatment." (PMID 39979285, 2025). "We found that CRC cell death caused by MLKL inactivation is enhanced by homoharringtonine (HHT), a drug used to treat chronic myelogenous leukemia." (PMID 39979285, 2025). "In contrast, a ribosomal inhibitor HHT, an alkaloid, also known as omacetaxine, used for treatment of chronic myelogenous leukemia, strongly cooperated with MLKL KO in reducing clonogenic survival and the total number of DLD1 cells." (PMID 39979285, 2025).
chronic obstructive pulmonary disease (2 papers, 2022 to 2023). A chronic and progressive lung disorder characterized by the loss of elasticity of the bronchial tree and the air sacs, destruction of the air sacs wall, thickening of the bronchial wall, and mucous accumulation in the bronchial tree. "A recent study reported that phosphorylated RIPK3 and MLKL signaling promotes inflammation, airway remodeling, and emphysema in chronic obstructive pulmonary disease (COPD) in the lung tissue of COPD patients." (PMID 35806033, 2022).
cognitive decline (2 papers, 2025). "Interventions inhibiting key necroptosis molecules such as RIPK1, RIPK3, and MLKL may hold promise for mitigating AD-related pathology and cognitive decline." (PMID 40161268, 2025).
colorectal tumor (2 papers, 2021 to 2022). "Moreover, the expression of MLKL was inversely linked to the stages of disease progression in colorectal tumors." (PMID 33767595, 2021). "Notably, low MLKL expression in human colorectal tumors, which enhanced STAT3 activation, was associated with decreased overall survival." (PMID 33767595, 2021). "To examine the potential role of MLKL in human colorectal tumors, we analyzed MLKL expression colorectal tumor samples." (PMID 33767595, 2021). "Notably, we observed that reduced MLKL expression in patients with colorectal tumors was correlated with high histological grade and decreased overall survival." (PMID 33767595, 2021). "Given our findings that loss of MLKL increased activation of STAT3 in spontaneous intestinal tumorigenesis, we further examined the potential correlation between MLKL expression and STAT3 activation in human colorectal tumor samples." (PMID 33767595, 2021). "In contrast to these studies, a recently published study reported that RIPK3 deficiency or MLKL deficiency had no impact on inflammation-associated or sporadic colorectal tumor development in mice, suggesting that necroptosis is rather irrelevant for CRC development." (PMID 36077828, 2022). "Necroptosis in tumor cells appears to be a favorable factor for colorectal tumor clearance, as downregulation of several of the key molecules in necroptotic signaling, such as RIPK3 and MLKL, are related to poor prognosis in CRC." (PMID 36077828, 2022). "We further found that reduced MLKL expression was correlated with poor prognosis and STAT3 hyperactivation in colorectal tumors." (PMID 33767595, 2021). "Furthermore, we saw that there was a negative relationship between MLKL and the STAT3 target genes expression in colorectal tumors." (PMID 33767595, 2021).
demyelinating disease (2 papers, 2025). A broad group of disorders that affect the myelin sheaths that cover the neurons. "Our observations of demyelinating disorder‐like behaviours and pathology caused by dysregulated MLKL, along with studies using EAE mice to investigate shared molecular signatures, were particularly revealing." (PMID 40490945, 2025). "Demyelination induced by unregulated MLKL in Optn ‒/‒ mice contributed extensively to significant defects that bore a resemblance to demyelinating disorders." (PMID 40490945, 2025). "It is also plausible that non-necroptotic MLKL activity may be triggered by an as-yet-unknown event, such as that which has been posited for demyelinating diseases." (PMID 39532538, 2025). "Collectively, these data suggested that the intricate link between MLKL and OPTN that serves to maintain myelin, with dysregulation of this balance resulting in severe impairments in motor functions and behaviours reported typically in MS and MS‐like demyelinating disorders." (PMID 40490945, 2025).
depression (2 papers, 2021 to 2022). "In the current study, we found a reduced number of astrocytes and elevated levels of necroptosis kinases, including RIPK1/p-RIPK1, RIPK3/p-RIPK3, and MLKL/p-MLKL, in hippocampal astrocytes of depression-like behavior mice." (PMID 36686688, 2022). "We raised another hypothesis that fluoxetine may inhibit RIPK1/RIPK3/MLKL-induced necroptosis of astrocytes in MDD to protect astrocyte injury and to reduce proinflammatory cytokines (such as IL-6 and TNF-α) induced by depression disorder." (PMID 36686688, 2022). "In order to explore the possible mechanism of necroptosis in the mouse model of depression, the expressions of RIPK1, RIPK3, MLKL, p-MLKL were detected by western blot assay." (PMID 34867405, 2021).
epilepsy (2 papers, 2024 to 2025). A brain disorder characterized by episodes of abnormally increased neuronal discharge resulting in transient episodes of sensory or motor neurological dysfunction, or psychic dysfunction. "Pharmacological inhibition of MLKL by morin significantly improves epilepsy, restoring cognitive decline and memory impairment and the preserving hippocampal neurons." (PMID 40070567, 2025). "Similarly, the MLKL/PGAM5/Drp1 pathway can be activated in epilepsy, a neurological condition affecting thoughts and behaviors." (PMID 40070567, 2025).
keloid (2 papers, 2022). An irregularly shaped, elevated mark on the skin caused by deposits of excessive amounts of collagen during wound healing. "Compared with normal skin fibroblasts, there were more TUNEL staining-positive cells, higher RIPK1 and RIPK3 expressions as well as MLKL phosphorylation in keloid fibroblasts (P < 0.01), which were all reversed by NaHS pretreatment (P < 0.01)." (PMID 35774378, 2022). "RIP3- and p-MLKL-positive cells significantly infiltrated the transitional region of keloid tissue." (PMID 35757697, 2022).
lung diseases (2 papers, 2022 to 2026). "In this manuscript, we review abnormal RIP1/RIP3/MLKL pathway activation and the mechanisms of action during the pathogenesis of lung diseases in children and provide new ideas for the prevention and treatment of NEC in children with lung diseases." (PMID 35967568, 2022). "Mixed lineage kinase domain-like protein (MLKL)-mediated necroptosis, an essential form of regulated cell death implicated in various pulmonary disorders, has not been fully investigated in the context of BPD." (PMID 41608843, 2026).
MODY (2 papers, 2022 to 2023). "Similarly, in the case of MODY diabetes, the heterozygous MLKL loss-of-function mutation also segregated with heterozygous deleterious mutations in the known MODY gene PDX1, as well as ERN2, NIPAL4 and SPTBN4 in affected individuals." (PMID 36755069, 2023). "Importantly, such studies can also prompt examination of potential risk posed by other human MLKL LOF and missense variants to the incidence of MODY." (PMID 35166320, 2022).
neuroblastoma (2 papers, 2023). Neuroblastoma (NB) is the most common solid, extracranial childhood tumor. "However, human neuroblastoma SH‐SY5Y cells did not express GSDMD, and infection did not induce phosphorylation of MLKL, a necroptosis marker, in SH‐SY5Y cells." (PMID 37646198, 2023).
neuropathy (2 papers, 2024 to 2025). A disorder affecting the nervous system that manifests with pain, tingling, numbness, and/or muscle weakness. "Similarly, the MLKL inhibitor necrosulfonamide has been shown to alleviate neuropathy in AD by specifically targeting the MLKL‐dependent necroptosis pathway." (PMID 39619229, 2024).
parasite infections (2 papers, 2023 to 2025). "To confirm that the reduction of parasitemia with TNF-α and Z-VAD-FMK in the presence of RIPK3 and MLKL was due to necroptosis, we assessed host cell survival during infection by measuring cell membrane integrity." (PMID 41055414, 2025). "While the expression levels of KLRG1 and PD-1 in T cells are normally increased during viral, bacterial or parasite infections, we found that the levels of KLRG1 and PD-1 in T cells remain the same regardless of MLKL status in MMTV-PyMT model (Extended Data." (PMID 36703228, 2023).
preeclampsia (2 papers, 2017 to 2026). Preeclampsia is a hypertensive disorder of pregnancy that is characterized by new-onset hypertension with proteinuria presenting after 20 weeks of gestation, and depending on mild or severe forms may initially present with severe headache, visual disturbances, and hyperreflexia. "In preeclampsia, increased necrosome (RIP1/RIP3) protein levels, as well as MLKL activation and oligomerization associated with necrotic cytotrophoblast morphology." (PMID 28151467, 2017). "Furthermore, the monomeric form of p-MLKL was restricted to the cytoplasmic compartment and was slightly increased in preeclampsia relative to controls (second panel)." (PMID 28151467, 2017).
prostate adenocarcinoma (2 papers, 2022 to 2023). "In prostate adenocarcinoma (PRAD), both the hormone ER and EMT signaling pathways are activated by MLKL and RIPK3." (PMID 37000317, 2023).
schwannoma (2 papers, 2014 to 2020). A benign, usually encapsulated slow growing tumor composed of Schwann cells. "It has been revealed that the artemisinin analog artesunate effectively induces necroptosis in RT4 schwannoma cells and human primary schwannoma cells by facilitating MLKL phosphorylation." (PMID 33665167, 2020). "Consistently, we observed that ART induced the necroptotic morphology decorated by p-MLKL in RT4 schwannoma cells and primary schwannoma cells." (PMID 25321473, 2014).
ulcerative colitis (2 papers, 2022 to 2023). An inflammatory bowel disease involving the mucosal surface of the large intestine and rectum. "The underlying protective mechanism was found to be associated with the regulation of necroptosis mediated by the RIP1/RIP3/MLKL signaling pathway, which suggested that PA/CCMTS-P enemas could serve as a promising therapeutic strategy for ulcerative colitis." (PMID 36843930, 2023).
abscesses (1 paper, 2022). "Additionally, histopathology of the collected periapical lesion specimens in this study, positively stained for p-MLKL, mainly showed periapical granulomas and abscesses." (PMID 35708336, 2022).
adenoma (1 paper, 2022). A neoplasm arising from the epithelium. "Based on our data, MLKL gene expression in patients with large tumor size (macro adenoma) was significantly correlated with MLKL protein level in NFPA (P = 0.0091) and GHPPA (P = 0.0149) tumors." (PMID 34983494, 2022). "The lower expression of MLKL was also detected in invasive versus non-invasive, macro adenome versus micro adenoma of NFPA and GHPPA tumors." (PMID 34983494, 2022).
adenovirus infection (1 paper, 2017). "Our data are also intriguing in that, in the absence of caspase inhibition, knockdown of RIPK3, but not MLKL, partially reduces cytotoxicity, suggesting that there may be other death effector proteins that are activated by RIPK3 in the presence of adenovirus infection." (PMID 29238045, 2017).
age (1 paper, 2023). A temporal measurement of the time period elapsed since an identifiable point in the life cycle of an organism. "Our observations of both delayed age-related lymphocytosis and reduced focal inflammation are suggestive that MLKL’s absence may impede select features of the aging process." (PMID 36755069, 2023).
alcoholic cirrhosis (1 paper, 2018). "Furthermore, phospho-mixed lineage kinase-like protein (p-MLKL) a downstream molecule of RIPK3 in necroptosis pathway was also activated in the necrotic area in patients with alcoholic cirrhosis." (PMID 30596105, 2018).
aortic aneurysm (1 paper, 2021). A ruptured aneurysm located in the wall of the proximal portion of the descending aorta proceeding from the arch of the aorta. "Using antibodies specific to phosphorylated MLKL or CaMKII, we detected activation of both MLKL and CaMKII in CaCl2-induced mouse aortic aneurysm tissue." (PMID 34572045, 2021).
Astrocytomas (1 paper, 2023). "Considering the histological diagnosis, only Astrocytomas comprise patients with significantly distinct MLKL expression profiles, being higher in grade 3 subtype, the most aggressive form of LGGs." (PMID 37651429, 2023).
atrial fibrillation (1 paper, 2025). A disorder characterized by an electrocardiographic finding of a supraventricular arrhythmia characterized by the replacement of consistent P waves by rapid oscillations or fibrillatory waves that vary in size, shape and timing and are accompanied by an irregular ventricular response. "In a murine model of calcium chloride and acetylcholine (CaCl2-Ach)-induced atrial fibrillation, three weeks of swimming training reduced protein levels of RIP1, RIP3, and their phosphorylated forms, as well as decreased MLKL translocation to the cell membrane." (PMID 40161268, 2025).
bladder urothelial carcinoma (1 paper, 2023). "The expression levels of MLKL and CASP8 in tumor samples were higher than those in normal tissues in KIRC (Renal Clear Cell Carcinoma), KIRP (Papillary Renal Cell Carcinoma), and BLCA (Bladder Urothelial Carcinoma)." (PMID 37000317, 2023).
brain tumors (1 paper, 2022). "MLKL protein is widely found in many human organs and low expression in many tumor tissues, such as brain tumors." (PMID 36357839, 2022).
Chronic colitis (1 paper, 2018). A chronic inflammatory disease of the large intestine (colon, cecum and rectum). "In ADAM17ex/ex mice subjected to chronic colitis, we again detected no signals specific for pRIPK3 and pMLKL despite the clear presence of inactive, unphosphorylated RIPK3 and MLKL in all samples, further supporting our assumption that necroptotic signaling is compromised in ADAM17ex/ex mice." (PMID 29560122, 2018).
chronic liver failure (1 paper, 2020). Liver failure that develops slowly and gradually for some time, possibly for years, often as the result of cirrhosis, or malnutrition. "Circulating levels of total MLKL were also elevated in those with acute on chronic liver failure, and PBMC RIPK3 mRNA levels correlated with TNF, MLKL, and overall survival." (PMID 33353156, 2020).